PDZK1 (PDZ domain containing 1)
Diseases named in the same sentence as PDZK1 in open-access papers (continued):
Sharing a sentence is not in itself a finding about the gene and the disease.
atherosclerosis (6 papers, 2009 to 2024). A disease characterized by the build-up of fatty material and calcium deposition in the arterial wall resulting in partial or complete occlusion of the arterial lumen. "Hepatic PDZK1 inactivation can significantly affect plasma HDL metabolism and structure, leading to occlusive atherosclerosis in mice deficient in both apo E and PDZK1." (PMID 38474781, 2024). "To explore further the consequences of PDZK1 deficiency in apoE KO mice on atherosclerosis and the heart, we subjected mice to a more severe, cholate-containing atherogenic diet (Paigen diet)." (PMID 19956623, 2009). "In apoE-/-;PDZK1-/- mice, receipt of a Paigen diet results in further exaggeration of atherosclerosis with macrophage-rich lesions and occlusive coronary artery disease in association with extreme hypercholesterolemia." (PMID 25886360, 2015). "ApoE KO and PDZK1/apoE dKO mice were fed a high fat/high cholesterol diet supplemented with cholate (Paigen diet) for three months to study the consequences of PDZK1 gene inactivation on lipoprotein metabolism, atherosclerosis and coronary heart disease." (PMID 19956623, 2009). "Because of the increased plasma lipids in Paigen diet fed PDZK1/apoE dKO compared to apoE KO mice, we next evaluated atherosclerosis in the aortic roots and coronary arteries of these mice." (PMID 19956623, 2009). "PDZK1/apoE dKO mice fed with a high fat/high cholesterol diet (Western diet) develop increased aortic root atherosclerosis compared to apoE single KO mice, but fail to develop occlusive coronary artery disease and myocardial infarction." (PMID 19956623, 2009). "PDZK1 has been shown to be atheroprotective using the high fat/high cholesterol (‘Western’) diet-fed murine apolipoprotein E (apoE) KO model of atherosclerosis, presumably because of its role in promoting reverse cholesterol transport via SR-BI." (PMID 19956623, 2009). "We have previously shown that PDZK1 confers protection against aortic root atherosclerosis in apoE KO mice fed an atherogenic, Western-type, high fat/high cholesterol diet for 3 months." (PMID 19956623, 2009). "•This data gives insight into mechanisms by which PDZK1 influences atherosclerosis development." (PMID 30246067, 2018). "Both PDZK1/apoE dKO and apoE KO mice showed significant amounts of atherosclerosis." (PMID 19956623, 2009). "We previously showed that the inactivation of PDZK1 did not affect SR-BI levels in two cell types known to be implicated in development of atherosclerosis, macrophages and endothelial cells." (PMID 19956623, 2009). "In addition, it is possible that the loss of PDZK1 in apoE KO mice might influence atherosclerosis and coronary heart disease via, as yet not identified, SR-BI-independent pathways." (PMID 19956623, 2009).
breast tumors (3 papers, 2017 to 2023). "in-silico analysis finds that CXCL12–CXCR4 is associated with an increased expression of PDZK1, PI3k and Akt which lead the breast tumor towards metastasis." (PMID 28929029, 2017). "TCGA database analysis of 1080 breast tumors showed that RNF2 expression was positively correlated with estrogen signaling target genes expression (PDZK1, TFF1 and ESR1)." (PMID 36271315, 2023). "A significant correlation between 17B-estradiol plasma levels and PDZK1 mRNA expression has been shown in ER-α (+) breast tumors providing a link between Er-α and PDZK1." (PMID 33593445, 2021).
colitis (3 papers, 2012 to 2017). Inflammation of the colon. "We recently reported that the expression of the PDZ-adaptor protein PDZK1 (NHERF3) is strongly reduced in inflamed intestine of ulcerative colitis patients and murine models of colitis." (PMID 28223944, 2017). "In a comparative analysis we observed the PDZK1 downregulation also in the DSS (dextran sulphate sodium) model of colitis." (PMID 22848392, 2012). "We previously reported a strong decrease in the NHERF family member PDZK1 (NHERF3), which binds to NHE3 and regulates its function in a mouse model of colitis." (PMID 25271043, 2015).
liver cancer (3 papers, 2022 to 2024). An epithelial or non-epithelial malignant neoplasm that arises from the liver. "This suggests that low expression of PDZK1 inhibits the cell cycle progression of liver cancer cells and, therefore, tumor progression." (PMID 38532426, 2024). "Our studies in liver cancer have shown that high expression of PDZK1 in liver cancer correlates highly with PI3K-Akt pathway activation." (PMID 36052278, 2022). "In this study, we found that increased PDZK1 in human liver cancer, especially HBV-positive cancers, was related to enhanced P3IK-Akt signaling." (PMID 36052278, 2022). "Our study found that PDZK1 is a gene highly linearly correlated with HBV infection and may promote the occurrence and development of liver cancer by promoting the PI3K-Akt pathway and fatty acid metabolism." (PMID 36052278, 2022).
renal cell carcinoma (3 papers, 2021 to 2024). "Furthermore, in recent renal cell carcinoma studies, PDZK1 was found to inhibit tumor development and progression." (PMID 38669103, 2024).
cervical cancer (2 papers, 2024 to 2025). A primary or metastatic malignant neoplasm involving the cervix. "Genes such as Wiskott-Aldrich Syndrome Protein (WASP), IQ Motif Containing B1 (IQCB1), Myosin IF (MYOIF) and PDZ Domain Containing 1 (PDZD1) that favour cervical cancer prognosis were found to be expressed in HPV 16 positive macrophages." (PMID 40589751, 2025).
Chronic colitis (2 papers, 2015 to 2018). A chronic inflammatory disease of the large intestine (colon, cecum and rectum). "The first part of the present project investigated whether the strong decrease in the expression of the PDZ-adaptor PDZK1 that we had previously observed in a mouse model for chronic colitis was also found in humans with IBD." (PMID 25271043, 2015). "However, previous studies have demonstrated decreased expression of PDZK1 in both a mouse model of chronic colitis and in humans with inflammatory bowel disease, also suggesting that the regulation of inflammatory mediators is the probable mechanism of PDZK1 expression." (PMID 29415757, 2018). "We observed a strong downregulation of PDZK1 (NHERF3) but not of NHERF1 and NHERF2 messenger RNA (mRNA) and protein in a mouse model of chronic colitis." (PMID 25271043, 2015).
clear cell renal cell carcinoma (2 papers, 2022 to 2024). "PENG was expressed at a lower level in clear cell renal cell carcinoma, it inhibited tumor cell growth by increasing PDZK1 via sponging miR-15b." (PMID 35037556, 2022).
dyslipidemia (2 papers, 2009 to 2015). "The dramatic loss of hepatic SR-BI protein in the livers of Paigen diet-fed PDZK1/apoE KO mice clearly contributed to their dyslipidemia and possibly played a role to the relatively unusual murine early onset occlusive coronary artery disease." (PMID 19956623, 2009).
glioma (2 papers, 2024). A benign or malignant brain and spinal cord tumor that arises from glial cells (astrocytes, oligodendrocytes, ependymal cells). "All our results preliminarily confirmed that the loss of PDZK1 expression by siRNA inhibits glioma cell proliferation and induces cell apoptosis by preventing AKT1 phosphorylation." (PMID 38669103, 2024). "Our data indicated that PDZK1 may act as a cancer-promoting gene in glioma and may be an underlying therapeutic target for glioma." (PMID 38669103, 2024). "Promoter hypomethylation may cause high expression of PDZK1 in glioma." (PMID 38669103, 2024). "We then conducted a Transwell assay to evaluate the effects of PDZK1 on glioma cell invasion ability." (PMID 38669103, 2024). "Cox regression analysis showed that age, glioma grade, ve_90, vp_skew, PDZK1, vp_kurt, and kep_90, were significant predictors of OS, and age, Glioma grade, ve_90, ve_skew, and PDZK1 were predictive indicators for PFS." (PMID 38692010, 2024). "Overall, our study revealed that PDZK1 acts as a novel oncogene in glioma by binding to AKT1 and maintaining the activation of the AKT/mTOR signaling pathway." (PMID 38669103, 2024). "Knockdown of PDZK1 delayed cell growth, inhibited the cell cycle, and mediated apoptosis in glioma cells." (PMID 38669103, 2024). "The results also confirmed that PDZK1 was dramatically overexpressed in glioma specimens, which is in accordance with results from TCGA and CGGA data mining and analysis." (PMID 38669103, 2024). "Clinically, high expression of PDZK1 predicts a poorer prognosis for glioma patients than low expression of PDZK1." (PMID 38669103, 2024). "The methylation levels of the PDZK1 CpG island were also lower in glioma tissues than in normal brain tissues." (PMID 38669103, 2024). "We first found that the expression of PDZK1 was correlated with adverse outcomes in glioma patients." (PMID 38669103, 2024). "When the expression of PDZK1 was suppressed in glioma cells, the percentage of U251 cells in the G0/G1 phase increased from 58% to 66%, whereas the percentage of cells in the S phase decreased from 33% to 25%." (PMID 38669103, 2024). "In our study, differential gene expression analysis using the CGGA and TCGA datasets revealed that PDZK1 was highly expressed in glioma tissues and that the PDZK1 expression level was correlated with tumor histologic grade." (PMID 38669103, 2024). "The results showed that a low promoter DNA methylation level of PDZK1 was correlated with poor overall survival in patients with gliomas." (PMID 38669103, 2024). "By using the TCGA and CGGA glioma databases, we found that PDZK1 is expressed at high levels in glioma tissues." (PMID 38669103, 2024). "Western blotting was used to investigate the effect of PDZK1 knockdown on the AKT1/mTOR signaling pathway in glioma cells." (PMID 38669103, 2024). "The HUMAN PROTEIN ATLAS dataset was also utilized to analyze the protein expression level of PDZK1 in the cerebral cortex and glioma." (PMID 38669103, 2024). "In conclusion, our findings indicate that promoter hypomethylation of the PDZK1 promoter was the reason for the high expression of PDZK1 in glioma, and the methylation level of PDZK1 is a meaningful prognostic marker in glioma." (PMID 38669103, 2024). "PDZK1 shows good diagnostic performance in differentiating grade III and grade IV gliomas and is correlated with DCE-MRI perfusion parameters." (PMID 38692010, 2024). "Next, to verify the expression of PDZK1 in glioma, 10 normal brain tissues and 20 glioma tissues were obtained for real-time fluorogenic quantitative PCR." (PMID 38669103, 2024). "Overall, our results indicated that PDZK1 may play a cancer-promoting role in glioma and that PDZK1 expression may be a prognostic factor in glioma." (PMID 38669103, 2024). "Here, we first revealed that PDZK1 is expressed at high levels in gliomas." (PMID 38669103, 2024). "We also explored the mechanism by which PDZK1 suppresses glioma cell proliferation." (PMID 38669103, 2024).
glioma (continued). "Furthermore, by using the CGGA database (mRNAseq_325), we also found that the expression level of PDZK1 was correlated with glioma histologic grade." (PMID 38669103, 2024). "In conclusion, our results demonstrated that knockdown of PDZK1 significantly inhibits glioma cell proliferation and invasion, indicating that PDZK1 may play a critical role in gliomagenesis." (PMID 38669103, 2024). "Hence, our data indicate that PDZK1 acts as a tumorigenic gene in glioma by maintaining the activation of the AKT/mTOR signaling pathway." (PMID 38669103, 2024). "Moreover, survival curve analysis revealed longer survival times for glioma patients with relatively lower PDZK1 expression than for those with high PDZK1 expression in the CGGA (mRNAseq_325), TCGA (GEPIA:LGG) and GSE30074 datasets." (PMID 38669103, 2024). "Overall, this research illustrated that PDZK1 is overexpressed in glioma specimens." (PMID 38669103, 2024). "What is the level of PDZK1 protein expression between normal and glioma tissues?" (PMID 38669103, 2024). "Upregulated PDZK1 was demonstrated to be correlated with adverse prognosis in glioma patients." (PMID 38669103, 2024). "Next, we examined PDZK1 protein expression in normal brain tissues and glioma tissues." (PMID 38669103, 2024). "Coimmunoprecipitation confirmed that PDZK1 interacts with AKT1 in glioma cells." (PMID 38669103, 2024). "Knockdown of PDZK1 inhibits glioma cell proliferation and invasion in vitro." (PMID 38669103, 2024). "In our study, we found that PDZK1 formed a complex with AKT1 in glioma, suggesting that PDZK1 could directly affect the function of AKT1." (PMID 38669103, 2024). "Taken together, our results revealed that PDZK1 interacted with AKT1 and that knockdown of PDZK1 may inhibit the activation of the AKT-mTOR signaling pathway in glioma cells." (PMID 38669103, 2024). "Therefore, we investigated the effects of PDZK1 on the proliferation ability and colony formation ability of glioma cells." (PMID 38669103, 2024). "Consistently, PDZK1 was more highly expressed in glioma tissues than in normal tissues." (PMID 38669103, 2024). "Therefore, we next determined the methylation levels of the PDZK1 promoter in glioma by using the UALCAN database." (PMID 38669103, 2024). "Only 0.3% of the 1396 patients with gliomas presented with PDZK1 gene alterations." (PMID 38669103, 2024). "The promoter methylation levels of PDZK1 were lower in GBM specimens than in normal tissue specimens, indicating that promoter DNA hypomethylation may be the reason for the high expression of PDZK1 in glioma." (PMID 38669103, 2024). "This may be the mechanism by which PDZK1 acts as a tumorigenic gene for glioma." (PMID 38669103, 2024). "Our further studies revealed that knockdown of PDZK1 in glioma cells could inhibit glioma cell proliferation, colony formation and invasion, which confirmed that PDZK1 could be a cancer-promoting gene for glioma." (PMID 38669103, 2024). "In addition, these genes were used to further determine the possible role of PDZK1 in glioma cells." (PMID 38669103, 2024). "Moreover, our data also indicated that PDZK1 may be a potential therapeutic target for glioma." (PMID 38669103, 2024). "Knocking down PDZK1 led to cell cycle arrest and cell apoptosis by inhibiting the AKT/mTOR signaling pathway in glioma cells." (PMID 38669103, 2024). "Thus, PDZK1 may be a potential therapeutic target for glioma." (PMID 38669103, 2024). "This study investigated the relationship between PDZK1 expression and Dynamic Contrast-Enhanced MRI (DCE-MRI) perfusion parameters in High-Grade Glioma (HGG)." (PMID 38692010, 2024). "The PDZK1 protein was highly expressed in most glioma tissues but was not expressed in all normal brain specimens." (PMID 38669103, 2024). "To determine whether PDZK1 can mediate the cell cycle in glioma cells by interacting with AKT1, we used flow cytometry to investigate the effects of PDZK1 on cell cycle progression." (PMID 38669103, 2024).
glioma (continued). "Moreover, PDZK1 expression can distinguish between grade III and grade IV gliomas." (PMID 38692010, 2024).
Hypercholesterolemia (2 papers, 2009 to 2015). An increased concentration of cholesterol in the blood. "We found that the Paigen diet induced a more severe hypercholesterolemia and greater aortic atherosclerosis in PDZK1/apoE dKO mice than in the apoE KO controls." (PMID 19956623, 2009). "It is unknown whether such a diet attenuates PDZK1 expression in VSM, thereby potentially contributing to aberrant VSM proliferative and migratory responses in the setting of hypercholesterolemia." (PMID 25886360, 2015).
lymph node metastasis (2 papers, 2024). "High expression of PDZK1 was associated with lymph node metastasis, degree of differentiation, and clinical stage." (PMID 38532426, 2024). "TNBC patients with lower PDZK1 levels had a higher rate of lymph node metastasis and shorter overall survival (OS) time, suggesting that PDZK1 can serve as a predictor of metastasis and a poor prognosis in TNBC patients." (PMID 38604999, 2024).
myocardial infarction (2 papers, 2009 to 2021). Gross necrosis of the myocardium, as a result of interruption of the blood supply to the area, as in coronary thrombosis. "SMIM24 has an important paralog PDZK1, the downregulation of which can cause myocardial infarction-related fibrosis." (PMID 34539419, 2021). "Previously, we had shown that PDZK1 deficiency enhances aortic root atherosclerosis in apoE deficient mice on a Western-type high fat/high cholesterol diet, but did not markedly induce occlusive coronary arterial atherosclerosis or myocardial infarction." (PMID 19956623, 2009). "ApoE single KO mice hearts showed no myocardial infarction and only occasional, minimal amounts of fibrosis, while myocardial infarctions were observed in 7 out of 8 (88%) PDZK1/apoE dKO mice." (PMID 19956623, 2009). "Strikingly, in contrast to the Western diet, the Paigen diet induced development of occlusive coronary arterial atherosclerosis and myocardial infarction in PDZK1/apoE dKO mice not seen in apoE KO controls." (PMID 19956623, 2009). "However, unlike the case with Western diet feeding, we found that Paigen diet-fed PDZK1/apoE dKO, but not apoE single KO, mice were characterized by substantial occlusive coronary artery disease and the presence of myocardial infarctions." (PMID 19956623, 2009).
ovarian carcinoma (2 papers, 2012 to 2015). A malignant neoplasm originating from the surface ovarian epithelium. "Pdzk1 is linked to oestrogen-sensitivity in breast and ovarian cancers." (PMID 22260314, 2012).
prostate carcinoma (2 papers, 2023 to 2025). A carcinoma that arises from epithelial cells of the prostate gland. "In extending our transcriptomic analysis to human prostate cancers, we found low PDZK1 to also correlate with hyperactivation of the WNT/β-catenin pathway in this tumor type." (PMID 37225693, 2023). "Analysis of PTEN transcript levels indicated that gastric and prostate cancers with low PDZK1 expression do express PTEN." (PMID 37225693, 2023). "However, no significant PDZK1 upregulation was observed in LNCap and 22RV1, which may explain the not effective of IMP on androgen-dependent prostate cancer cells." (PMID 39819421, 2025).
ulcerative colitis (2 papers, 2015 to 2017). An inflammatory bowel disease involving the mucosal surface of the large intestine and rectum. "Biopsies from the colon of patients with ulcerative colitis, murine inflamed ileal and colonic mucosa, NHE3-transfected Caco-2BBe colonic cells with short hairpin RNA (shRNA) knockdown of PDZK1, and Pdzk1-gene-deleted mice were studied." (PMID 25271043, 2015).
aortic atherosclerosis (1 paper, 2022). A atherosclerosis that involves the aorta. "PDZK1/ApoE DKO mice developed greater diet-induced aortic atherosclerosis compared with control ApoE knockout mice when fed a high-fat, Western-induced atherosclerotic diet." (PMID 36052278, 2022).
coronary heart disease (1 paper, 2009). "In this study, we describe a new murine model of diet-induced coronary heart disease, the Paigen-diet-fed PDZK1/apoE dKO mouse." (PMID 19956623, 2009). "Thus, the Paigen diet-fed PDZK1/apoE dKO mice represent a new murine model of coronary heart disease and suggest that PDZK1 may represent a valuable target for therapeutic intervention." (PMID 19956623, 2009). "The PDZK1/apoE dKO mouse model joins a growing list of animal models that share features of classic human coronary heart disease and may thus prove useful for characterizing mechanisms underlying disease development and testing approaches for prevention and treatment." (PMID 19956623, 2009).